ACBD3 (acyl-CoA binding domain containing 3)
Diseases named in the same sentence as ACBD3 in open-access papers (continued):
Sharing a sentence is not in itself a finding about the gene and the disease.
tumor (5 papers, 2022 to 2025). "When exploring subgroups and tumor subtypes, high ACBD3 expression was associated with a higher probability of relapse and distant metastasis in patients." (PMID 36012147, 2022). "In addition, ACBD3 gene mutation analysis has shown that ACBD3 mutations exist in a variety of tumor cells, with missense mutations being the most common." (PMID 38098097, 2023). "High tumor ACBD3 was also associated with less overall survival in HER2- tumors." (PMID 36012147, 2022). "To explore the potential role of ACBD3 in TIME, we examined the correlation between ACBD3 expression and the levels of tumor-infiltrating lymphocytes." (PMID 40189704, 2025). "In epithelial cancer cells with impaired NOTCH activity, ACBD3 primarily activates the PI4KB-driven secretory pathway to promote tumor growth, particularly in 1q-LUAD cells." (PMID 40189704, 2025). "In this study, we investigated the function of ACBD3 in NSCLC progression and uncovered an unexpected dichotomous role of ACBD3 in tumor growth and metastasis." (PMID 40189704, 2025). "The gene expression profiling interactive analysis tool (GEPIA) was queried for ACBD3 transcription levels in different tissues, and most normal tissues were found to have lower expression of ACBD3 than their paired tumor samples." (PMID 36012147, 2022). "ACBD3 depletion impaired tumor growth, which can be restored by ectopic ACBD3 reconstitution." (PMID 40189704, 2025). "We have assumed that ACBD3 might play a potential role in the occurrence of tumor subtypes, and more experimental results are needed to support this theory." (PMID 38098097, 2023). "Previously published work by Huang and colleagues compared ACBD3 levels in tumor samples with normal tissue obtained from reduction mammoplasty, which could account for the differences observed in the two studies." (PMID 36012147, 2022).
ACBD3 also shares sentences with these, for which no sentence is quoted: hepatocellular carcinoma (2 papers); osteosarcoma (2); acute myeloid leukaemia (1); bacterial infection (1); bladder urothelial carcinoma (1); esophagus adenocarcinoma (1); esophagus squamous cell carcinoma (1); fibrosarcoma (1); glioma (1); invasive breast carcinoma (1); kidney cancer (1); kidney chromophobe (1); Obesity (1); Oral squamous cell carcinoma (1); ovarian serous cystadenocarcinoma (1); pancreatic adenocarcinoma (1); pheochromocytoma (1); primary pigmented nodular adrenocortical disease (1); prostate adenocarcinoma (1); prostate carcinoma (1); small cell lung carcinoma (1); uterine corpus endometrial carcinoma (1).